SULT1E1 (sulfotransferase family 1E member 1)
Description:
Sulfotransferase that utilizes 3'-phospho-5'-adenylyl sulfate (PAPS) as sulfonate donor to catalyze the sulfate conjugation of estradiol and estrone. Is a key enzyme in estrogen homeostasis, the sulfation of estrogens leads to their inactivation. Also sulfates dehydroepiandrosterone (DHEA), pregnenolone, (24S)-hydroxycholesterol and xenobiotic compounds like ethinylestradiol, equalenin, diethyl stilbesterol and 1-naphthol at significantly lower efficiency. Does not sulfonate cortisol, testosterone and dopamine. May play a role in gut microbiota-host metabolic interaction. O-sulfonates 4-ethylphenol (4-EP), a dietary tyrosine-derived metabolite produced by gut bacteria. The product 4-EPS crosses the blood-brain barrier and may negatively regulate oligodendrocyte maturation and myelination, affecting the functional connectivity of different brain regions associated with the limbic system.
Synonyms: ST1E1; STE; EST; EST-1
Tractability: Small molecule: a structure with a bound ligand is known; a high-quality ligand is known; it has a high-quality binding pocket. PROTAC: a small molecule that binds it is known.
Target class: Enzyme; Transferase
Gene: Protein-coding gene on chromosome 4 (69,838,259 to 69,861,075, reverse strand). Ensembl gene ENSG00000109193.
Subcellular location: Cytoplasm, cytosol
Subcellular location (Human Protein Atlas): Cytosol; Nuclear membrane
Pathways (Reactome):
Drug ADME: Paracetamol ADME
Metabolism: Cytosolic sulfonation of small molecules
Gene Ontology:
Molecular function: estrone sulfotransferase activity; flavonol 3-sulfotransferase activity; protein binding; steroid sulfotransferase activity; sulfotransferase activity; aryl sulfotransferase activity
Biological process: 3'-phosphoadenosine 5'-phosphosulfate metabolic process; estrogen catabolic process; estrogen metabolic process; ethanol catabolic process; positive regulation of fat cell differentiation; sulfation; steroid metabolic process; sulfur compound metabolic process
Cellular component: cytosol
Genetic constraint (gnomAD): Loss-of-function variants: 20 observed, 20.99 expected, observed/expected ratio (o/e) 0.95, 90% interval 0.67 to 1.38. The upper end of that interval is the gene's LOEUF score, 1.38, which puts it in group 5 of 6, group 1 being the genes least tolerant of losing a copy. Missense variants: 243 observed, 244.34 expected, observed/expected ratio (o/e) 0.99, 90% interval 0.89 to 1.11. Synonymous variants: 88 observed, 79.04 expected, observed/expected ratio (o/e) 1.11, 90% interval 0.94 to 1.33.
Homologues: Orthologues: chimpanzee SULT1E1 (99% identical), macaque SULT1E1 (96% identical), dog SULT1E1 (82% identical), guinea pig SULT1E1 (82% identical), rabbit SULT1E1 (81% identical), pig SULT1E1 (77% identical), mouse Sult1e1 (76% identical), rat Sult1e1 (70% identical), tropical clawed frog sult1b1 (48% identical), zebrafish sult1st9 (46% identical), zebrafish sult1st2 (46% identical), zebrafish sult1st1 (46% identical), and 10 more. Paralogues in human: SULT1B1 (56% identical), SULT1A1 (50% identical), SULT1A2 (49% identical), SULT1A3 (49% identical), SULT1A4 (49% identical), SULT1C3 (49% identical), SULT1C4 (49% identical), SULT1C2 (47% identical), SULT2A1 (35% identical), SULT2B1 (33% identical), SULT4A1 (33% identical), SULT6B1 (30% identical).
Diseases named in the same sentence as SULT1E1 in open-access papers:
SULT1E1 is named in the same sentence as 62 diseases in open-access papers, as found by Europe PMC text mining. Sharing a sentence is not in itself a finding about the gene and the disease. The quoted sentences say what the papers report.
breast carcinoma (25 papers, 2009 to 2025). "Several cohort studies have developed SULT1E1 association models, such as Predictors of Breast Cancer Recurrence (ProBeCaRE) and U-statistics-based tests for identifying the pathway-based candidate genes of breast cancer and hormone metabolism pathways." (PMID 33799763, 2021). "Tumor expression of SULT1E1 was also found to be positively correlated with ER-β and PR-B, which are associated with an improve prognosis for breast cancer." (PMID 32158360, 2020). "High SULT1E1 levels were found in breast cancer tissues and associated with a poor prognosis for breast cancer in women." (PMID 30710069, 2019). "SULT1E1 (estrogen sulfotransferase) is an important enzyme in hormone homeostasis regulation and biosynthesis, showing a high affinity for beta-estradiol (E2), and estrogen is associated with the growth and development of human breast cancer cells." (PMID 35528018, 2022). "In-situ inactivation of E2 is possible by SULT1E1 induction and it may be a way to decrease breast cancer risk." (PMID 32158360, 2020). "SULT1E1 polymorphisms are shown to be a risk factor for breast and endometrial cancers, suggesting that its modulation might be an attractive strategy in the prevention, management and or treatment of breast cancer." (PMID 39132498, 2024). "The current study explores the events of the redox dependent adverse regulations of SULT1E1 and possible foul-play of estradiol in breast cancer tissues of postmenopausal women." (PMID 39132498, 2024). "Under the purview of literature study, the objective of the current study was to explore the role of SULT1E1 and HIF1α proteins/genes expressions in human breast cancer tissues in relation to this disease severity." (PMID 39132498, 2024). "The current manuscript clearly shows the redox regulation of SULT1E1 and other radical-metabolizing enzymes in the pathogenesis of human breast cancer of different stages." (PMID 32158360, 2020). "This is important that the level of SULT1E1 expression is inversely correlated with malignancy in breast cancers." (PMID 32158360, 2020). "Here, oxidative stress-regulated SULT1E1-expression was analyzed in human breast carcinoma-tissues and in rat xenografted with human breast-tumor." (PMID 32158360, 2020). "In our study, SULT1E1 is contrarily expressed in breast cancer patients along with an increased oxidative stress in both the surrounding and tumor." (PMID 32158360, 2020). "This suggests a major role of estrogen metabolizing enzymes like aromatase, sulfatase, 17β-HSD and SULT1E1 in breast cancer." (PMID 32158360, 2020). "The majority of human breast cancer cell lines are known to express extreme low levels of SULT1E1 compared to normal human mammary epithelial cells." (PMID 36312461, 2019). "Majority of human breast cancer cell lines express extreme low levels of SULT1E1 compared to normal mammary cells." (PMID 36312461, 2019). "Our results also suggest that SULT1E1 inducer has an additive or synergistic effect on the inhibition of MCF-7 cell proliferation when combined with other known breast cancer drugs." (PMID 36312461, 2019). "The majority of human breast cancer cell lines are known to express very low levels of SULT1E1 compared to normal mammary cells." (PMID 36312461, 2019). "Our data suggest that certain nutritional flavonoids induce SULT1E1 and inhibit cell proliferation in estrogen-dependent breast cancer MCF-7 cells." (PMID 36312461, 2019). "Stable expression of SULT1E1 in human breast cancer cells has been reported to significantly inhibit cell growth at physiologically relevant estradiol concentrations." (PMID 36312461, 2019). "Experimental data showed that SULT1E1 overexpression inhibited proliferation, migration, invasion of breast cancer cells by mediating the adaptive response to estrogen in tumor cells." (PMID 30710069, 2019). "Report reveals that SULT1E1 level is inversely correlated with the degree of malignancy in breast cancers." (PMID 31114446, 2019).
breast carcinoma (continued). "SULT1E1 is known to be overexpressed (relative to breast cancer cells) in normal human mammary epithelial cells." (PMID 27322429, 2016). "In this descriptive study, correlations were examined between concentrations of tamoxifen metabolites and genotypes for CYP2D6, CYP3A4, CYP3A5, SULT1A1, SULT1A2 and SULT1E1 in 135 patients with estrogen receptor-positive breast cancer." (PMID 23922954, 2013). "Indeed, these drugs have been shown shown to have preventive effects on breast cancer by stimulating the expression of sulfotransferase SULT1E1, which plays a role in deactivating estrogens." (PMID 40551152, 2025). "Limitations in 1E1 activity might be due to its inactivation in oxidative stress in breast cancer, where Cys83 of SULT1E1 may remain in oxidized state and hinders E2 binding and sulfo-conjugation by this enzyme." (PMID 39132498, 2024). "Our previous report suggests that oxidative stress induced SULT1E1 modifications may be similar in human breast cancer tissue and experimental animal model." (PMID 39132498, 2024). "Regulating estrogen levels, which is especially related to SULT1E1’s sulfation capacity, could facilitate the development of breast cancer or its avoidance in Korean females." (PMID 33799763, 2021). "Indeed, glucocorticoids were shown to have preventive breast cancer effects by stimulating the expression of sulfotransferase SULT1E1 (which plays a role in deactivating oestrogens)." (PMID 34340701, 2021). "Moreover, the concentrations of E1S and E2S are higher in patients with breast fibroadenoma; however, in that same study, the expression of SULT1E1 decreased or was abolished in breast cancer tissues, though it was expressed in normal breast cells." (PMID 33799763, 2021). "Activation of GR induces SULT1E1 which may be an essential pathway in breast cancer patients where GR is influenced by oxidative stress." (PMID 32158360, 2020). "This study evidently proofs that the variation in Nrf2 expression and activation as a transcription factor may play an important role in breast cancer patients via induction of SULT1E1 what we have noticed in our immunohistochemical study." (PMID 32158360, 2020). "Therefore, the aim of this work is to study the role of SULT1E1 in breast cancer tissue, its regulation and its expression." (PMID 32158360, 2020). "Hence our study shows that severe stages of breast cancer maintains a perfect balance of oxidants, antioxidant, E2, SULT1E1 along with genes responsible for proliferation and apoptosis via Nrf2 and NFκβ." (PMID 32158360, 2020). "This study also aimed to correlate oxidative stress status and SULT1E1 expression in breast cancer in order to find whether oxidative stress influences SULT1E1 in breast carcinoma." (PMID 32158360, 2020). "Redox regulation of SULT1E1 as reported in in vitro studies may also attributes to low SULT1E1 activity in breast cancer." (PMID 31114446, 2019). "It is suggested that E2S level is lower than E2 in breast cancer, indicating low SULT1E1 activity." (PMID 31114446, 2019). "Thus, ERα activation is important in regulating STS activity and subsequent E1 and E2 synthesis, although a full understanding of what regulates STS and SULT1E1 expression and activity in breast cancer remains to be elucidated." (PMID 26213785, 2015). "Furthermore, SULT1E1 expression, responsible for E1 sulfation, is decreased in breast cancer, with an inverse correlation between tumor histological grade and levels of intratumoral SULT1E1 immunoreactivity." (PMID 26213785, 2015). "However, the role of SULT1E1 was not examined in cervical cancer, though high SULT1E1 levels have been found in the tumor tissues of patients with breast cancer and have been associated with a poor prognosis for breast cancer in women." (PMID 37350944, 2023). "It indicates that Nrf2 may be the transcriptional regulator of SULT1E1 in case of breast cancers." (PMID 32158360, 2020).
breast carcinoma (continued). "Induction of SULT1E1 in breast cancer patients may provide new treatment strategies." (PMID 31114446, 2019). "So, CAR mediated SULT1E1 induction may be utilized to control E2 induced breast cancer." (PMID 31114446, 2019). "Induction of intra-tumoral SULT1E1 and reduction of estrogen concentration by TM208 contributes to the anti-breast cancer action." (PMID 32158360, 2020). "In this work, we studied the gene regulation of human SULT1E1, in human breast cancer cell line MCF-7, by certain breast cancer drugs and flavonoids." (PMID 36312461, 2019). "The novel combination of DAS and chalcone might be invaluable, because oxidative stress not only inactivates SULT1E1 but also augments Nrf-2 and HIF-1a in breast cancer." (PMID 39132498, 2024). "There are no literature reports on studies of SULT1E1 gene induction in breast cancer cells." (PMID 36312461, 2019).
endometrial cancer (6 papers, 2011 to 2023). Primary or metastatic malignant neoplasm involving the endometrium (mucous membrane that lines the endometrial cavity). "Furthermore, Sult1e1 polymorphisms are shown to be a risk factor for breast and endometrial cancers." (PMID 21698271, 2011). "SULT1E1 was found to be correlated with estrogen-dependent breast and endometrial cancer while the expression level remains controversial." (PMID 30710069, 2019). "The expression of SULT1E1 is highly related to breast and endometrial cancers since it could inactivate estrogens in vivo." (PMID 37396163, 2023). "Therefore, gene up-regulation of SULT1E1 could provide novel possibilities for the treatment of estrogen-dependent breast and endometrial cancers." (PMID 36312461, 2019). "Therefore, the up-regulation of SULT1E1 gene may provide novel possibilities for the treatment/prevention of patients with estrogen-dependent breast and endometrial cancers." (PMID 36312461, 2019). "Additionally, the SNP rs6259 in the promoter region of SULT1E1 has been associated with increased risk of endometrial cancer, and SNPs *959 G>A and IVS4-1653 T>C with increased recurrence of endometrial cancer." (PMID 26924986, 2016). "Although the expression of the STS and SULT1E1 genes in diseased vs. control endometrium has differed between studies, all of the published data show higher mRNA and protein levels for STS than SULT1E1 in endometrial cancer tissue vs. control endometrium." (PMID 26924986, 2016).
pancreatic cancer (6 papers, 2011 to 2023). "The expression of LZIC, FXR, SCAMP1, and SULT1E1 was significantly higher in pancreatic cancer tissues with LN metastasis than in pancreatic cancer tissues without LN metastasis." (PMID 21364590, 2011). "In summary, microarrays together with real-time PCR validation results clearly show that the expression of LZIC, FXR, SCAMP1, and SULT1E1 were confirmed to be significantly higher in pancreatic cancer tissues with LN metastasis than in pancreatic cancer tissues without LN metastasis." (PMID 21364590, 2011).
prostate carcinoma (6 papers, 2017 to 2025). A carcinoma that arises from epithelial cells of the prostate gland. "SULT1E1 catalyzes the sulfation of estrogens, which play a vital regulatory role in the development and propagation of reproductive malignancies such as breast and prostate cancer." (PMID 35326723, 2022). "Notably, the CERES scores of B4GALT4 and SULT1E1 were not less than zero in some prostate cancer cell lines, indicating that B4GALT4 and SULT1E1 might not play an inhibitory role in PRAD." (PMID 36439479, 2022).
type 2 diabetes (5 papers, 2013 to 2021). "Hepatic SULT1E1 expression, although normally low, is elevated in type 2 diabetic mice, and loss of SULT1E1 improved metabolic function in these same animals." (PMID 26213785, 2015). "Loss of SULT1E1 improves the metabolic function in a female mouse model of type 2 diabetes, restores insulin sensitivity, and blocks hepatic gluconeogenesis and lipogenesis." (PMID 23476785, 2013). "A mouse study also showed that increased unsulphated-estrogen availability due to loss of SULT1E1 improved metabolic function in a model of type 2 diabetes, which leads to speculations about a potential role of SULT1E1 inhibition for this disease - at least in women." (PMID 30283331, 2018). "Likewise, diabetes type 2 mouse models (db/db and ob/ob) also exhibited the hepatic overproduction of SULT1E1, representing SULT1E1’s role in maintaining the balance of estrogen sulfation." (PMID 33799763, 2021). "Since extragonadal estrogen production is typical for primates, the benefit of increasing levels of active estrogens by reducing SULT1E1 may have to be studied in a proper model for type 2 diabetes in this group." (PMID 23476785, 2013). "The authors suggest that inhibition of SULT1E1 at least in females may represent a novel approach in the therapy of type 2 diabetes." (PMID 23476785, 2013). "In type 2 diabetes, induction of hepatic SULT1E1 is most frequently observed." (PMID 23476785, 2013).
ovarian carcinoma (4 papers, 2016 to 2021). A malignant neoplasm originating from the surface ovarian epithelium. "The enzymes that catalyze these reactions (i.e., HSD17B2, AKR1C3, SULT1E1) were detected by immunohistochemistry in ovarian cancer tissue samples." (PMID 28674494, 2017). "Significantly decreased expression of SULT1E1 was seen at the mRNA level in epithelial ovarian cancer cells compared to ovarian surface epithelial cells." (PMID 28674494, 2017). "The importance of the local formation of E2 via the sulfatase pathway is supported by high levels of STS and significantly down-regulated SULT1E1 together with metabolism of E1-S to E1 and E2 in tissue samples and model cell lines of ovarian cancer." (PMID 28674494, 2017).
Obesity (3 papers, 2015 to 2022). Accumulation of substantial excess body fat. "This evidence suggests an importance in both STS and SULT1E1 activity in improving metabolic outcomes associated with obesity." (PMID 26213785, 2015). "Thus, estrogen action in obesity will be regulated by steroid sulfation because the estrogen sulfotransferase SULT1E1 is highly expressed in adipose tissue of male mice and induced by T in female mice." (PMID 26213785, 2015). "Upregulation of Sult1e1 which is responsible for sulfation and inactivation of estrogen, is reported in db/db mice, and this may be mediated by LXR-dependent transactivation as LXR is frequently induced in obesity and fatty livers." (PMID 28797077, 2017).
breast tumor (2 papers, 2018 to 2020). "In our study, an increased SULT1E1 expression is noticed in breast tumor samples as compared to their corresponding surrounding tissue and comparatively low in some tumors resulting poor prognosis." (PMID 32158360, 2020). "In breast tumor tissue, steroid sulfation is catalyzed by SULT1E1, SULT1A1, and SULT2A1." (PMID 30042681, 2018). "Breast tumors NPSH level may provide a localized reducing environment where active Keap1 may negatively regulate Nrf2 and hinders the SULT1E1 expression as in few patients." (PMID 32158360, 2020).
cystic fibrosis (2 papers, 2020 to 2021). Autosomal recessive disorder caused by pathogenic variants in the CFTR gene (cystic fibrosis transmembrane conductance regulator), which encodes a chloride and bicarbonate channel expressed in epithelial cells, and follow the diagnosis criteria. "It has previously been reported that SULT1E1 is expressed in hepatocytes, and its activity was significantly elevated in the livers of cystic fibrosis-associated liver disease model mice." (PMID 33317575, 2020). "According to a study on cystic fibrosis, which is an inherited disorder and affects the lung, intestine, pancreas, and livers, hepatic Sult1e1 activity was increased in cystic fibrosis transmembrane conductance regulator (CFTR) −/− mice compared with CFTR+/+." (PMID 34539442, 2021).
diabetes (2 papers, 2013 to 2020). "Thus, this CAR-phosphorylated ERα signaling enables these two nuclear receptors to communicate, activating the Sult1e1 gene in response to either PB or diabetes in mice." (PMID 32193417, 2020).
osteosarcoma (2 papers, 2018 to 2020). A usually aggressive malignant bone-forming mesenchymal neoplasm, predominantly affecting adolescents and young adults. "In conclusion, this study identified statistically significant associations for a genetic variant in SULT1E1 with MTX plasma levels and three genetic variants in CYP2B6 and CYP4F8 with thrombocyte counts after HD-MTX infusion in osteosarcoma patients." (PMID 32903464, 2020).